PIEZO1 (piezo type mechanosensitive ion channel component 1 (Er blood group))
Diseases named in the same sentence as PIEZO1 in open-access papers (continued):
Sharing a sentence is not in itself a finding about the gene and the disease.
skin aging (2 papers, 2024). The gradual irreversible changes in structure of skin that occur as a result of the passage of time.. "Therefore, investigating how biomaterials like PLLA, with varying stiffness levels, affect Piezo1 activation and subsequent fibroblast responses could provide valuable insights into the mechanobiology underlying skin aging and rejuvenation." (PMID 39000341, 2024). "In conclusion, our study highlights the potential of RF treatment as a promising intervention against skin aging, elucidating its ability to modulate key cellular components, including HSPs and Piezo1." (PMID 38791217, 2024).
Splenomegaly (2 papers, 2022 to 2025). Abnormal increased size of the spleen. "Mice harboring a gain-of-function variant of Piezo1 specifically in erythroid-lineage cells were also previously found to develop hemolytic anemia and consequent splenomegaly, and their RBCs showed increased resistance to hypotonic stress." (PMID 40533105, 2025).
temporal lobe epilepsy (2 papers, 2024). A localization-related (focal) form of epilepsy characterized by recurrent seizures that arise from foci within the temporal lobe, most commonly from its mesial aspect. "In temporal lobe epilepsy, Piezo1 expression is increased on astrocytes and other glio-vascular elements in correlation with the pro-inflammatory biomarkers in of humans." (PMID 38612801, 2024). "Similarly, Piezo1 is upregulated within an inflammatory milieu in a pre-clinical model of mesio-temporal lobe epilepsy, and, accordingly, TNFα upregulated Piezo1 expression in astrocytes." (PMID 38534326, 2024).
thoracic aortic aneurysm (2 papers, 2022 to 2024). An aneurysm formed in the wall of the proximal portion of the descending aorta proceeding from the arch of the aorta. "The PBS proband in our report has Supraventricular tachycardia (SVT) and his brother with unknown PIEZO1 variant status (no DNA available for study) has thoracic aortic aneurysm and dissection (TAAD)." (PMID 38184690, 2024).
Ureteral obstruction (2 papers, 2021 to 2024). Obstruction of the flow of urine through the ureter. "However, the early activation and upregulation of Piezo1 after unilateral ureteral obstruction may be attributed to the increased pressure in the lumen of the tract or the mechanical stretch of the epithelial cells caused by the dilatation of the upper urinary tract and the hydrops urine pool." (PMID 38362490, 2024). "We also explored Piezo1 expression was positively correlated with the strength of EMG activity in the ureter and with the strength of ureteral contractility after ureteral obstruction, but the specific mechanism still needs further study." (PMID 38362490, 2024).
Varicose veins (2 papers, 2020 to 2025). Enlarged and tortuous veins. "We identified a novel association between PIEZO1 LOF variants (cumulative allele frequency = 0.18%) and increased risk for varicose veins (OR = 4.9, P = 3.2 × 10−8)." (PMID 33087929, 2020). "Our data not only provide support for PIEZO1 as the causal gene in this locus, but also clarify the direction of effect, as the loss of gene function in carriers with heterozygous LOF variants leads to an increased risk of developing varicose veins." (PMID 33087929, 2020).
viral infection (2 papers, 2023 to 2025). "Our data further revealed that magnesium-sufficiency is involved in Piezo1-directed NET formation to regulate macrophage differentiation during the response to virus infection." (PMID 39890818, 2025). "Using clodronate liposomes to deplete macrophages in mice, we investigated the role of macrophage differentiation induced by Piezo1−/− neutrophil NET DNA in viral infection in mice." (PMID 39890818, 2025). "After virus infection, Piezo1 channel activation was downregulated by GsMTx4 treatment, leading to reduced PAD4 expression, ROS production and NET formation in neutrophils, and TNFα and NOS2 expression was decreased in macrophages from the BALF and lung." (PMID 39890818, 2025). "Our data showed that SIRT2–HIF1α, a redox-related mechanism, is required for regulating PAD4–ROS signalling-mediated NET formation in Piezo1−/− neutrophils during the immune response to viral infections." (PMID 39890818, 2025). "Piezo1-deficient mice presented similar numbers of infiltrating neutrophils and macrophages in the BALF and lungs as WT mice following virus infection." (PMID 39890818, 2025). "A low-magnesium diet ameliorates Piezo1-mediated NET formation and M1 macrophage differentiation, which contributes to relieving inflammation caused by virus infection." (PMID 39890818, 2025). "Taken together, these data reveal that Piezo1 is required for NET DNA production in neutrophils for macrophage differentiation during virus infection." (PMID 39890818, 2025). "Is macrophage differentiation induced by neutrophil NETs induced by Piezo1 necessary for combating viral infection?" (PMID 39890818, 2025). "Genetic deletion of Piezo1 in neutrophils inhibited the generation of NETs and M1 macrophage differentiation while driving the development of M2 macrophages during viral infection." (PMID 39890818, 2025). "It is likely that cytoskeletal disruptions induced by viral infection change the biomechanical properties of EV-A71-infected cells, leading to Piezo1 activation and subsequent extrusion." (PMID 36914754, 2023). "Interestingly, after virus infection in mice, Piezo1−/− mice presented reduced TLR9, cGAS, STING and IRF3 expression in macrophages in the BALF." (PMID 39890818, 2025). "To screen the key molecules that play an integrated regulatory role downstream of Piezo1, we analysed the neutrophil data of virus infection via RNA sequencing and identified 18 target molecules in the integrated region of the three regulatory-related signalling pathways." (PMID 39890818, 2025). "Taken together, these data suggest that the cGAS–STING signalling pathway is required for neutrophil NET DNA-induced M1 macrophage differentiation during virus infection, and we further hypothesized that Piezo1 plays a regulatory role in antiviral immunity." (PMID 39890818, 2025). "Finally, we tested the application of a pharmacological approach to target Piezo1 in neutrophils and determined whether our findings recapitulated our previous findings derived from the genetic targeting of Piezo1 in mice during viral infection." (PMID 39890818, 2025). "How does Piezo1 regulate neutrophil NET formation and M1 macrophage differentiation after virus infection?" (PMID 39890818, 2025). "In summary, targeting the ion channel sensor Piezo1 in neutrophils alters NET DNA production and TLR9 and cGAS signalling activities, thereby contributing to the reciprocal differentiation of M1 and M2 macrophages while responding to viral infection." (PMID 39890818, 2025). "Under normal and viral infection conditions, magnesium at a physiological concentration (0.6 mM) increased NET formation and the expression of PAD4, SIRT2 and HIF1α; upregulation of Piezo1 expression by Yoda1 treatment promoted these effects, but Piezo1−/− abolished these alterations." (PMID 39890818, 2025).
viral infection (continued). "The ion channel Piezo1, as a signal node, senses the magnesium concentration and integrates the downstream SIRT2–HIF1α signalling pathway to direct NET formation during the response to viral infection." (PMID 39890818, 2025). "Piezo1−/− or Piezo1 upregulation by Yoda1 treatment altered SIRT2 and HIF1α expression in neutrophils, indicating that SIRT2 and HIF1α are likely involved in Piezo1-mediated NET formation in neutrophils during the response to virus infection." (PMID 39890818, 2025).
acute kidney injuries (1 paper, 2025). "Importantly, myeloid-specific deletion of PIEZO1 in mice provided protective effects against IR-AKI, highlighting the potential therapeutic value of targeting the PIEZO1–NOTCH1 axis in acute kidney injuries." (PMID 40724850, 2025).
adenomyosis (1 paper, 2026). The growth of endometrial tissue inside the muscular wall of the uterine corpus. "While our study focused on adenomyosis-associated dysmenorrhea, the PIEZO1-eNOS aberration might also occur in other uterine disorders such as fibroids, and may also be a contributing factor for embryo implantation failure because of adenomyosis or other pathologies." (PMID 41836349, 2026). "The link between PIEZO1 and eNOS, along with the discovery of PIEZO1 hypermethylation and its downstream target eNOS, highlights the importance of mechanotransduction in adenomyosis and the role of NO in uterine contractility." (PMID 41836349, 2026). "Consistent with the human data, mice with induced adenomyosis exhibited reduced Piezo1 and eNos staining and elevated Piezo2 and Otr staining in myometrium, concordant with increased fibrosis." (PMID 41836349, 2026).
advanced heart failure (1 paper, 2023). Patients with advanced heart failure have severe limitations, experiences symptoms even while at rest and are mostly bedbound patients. "To further validate these findings, we used immunohistochemical staining and Western blotting to confirm that Piezo1 was significantly increased in the myocardium of patients with advanced heart failure of DCM." (PMID 37303604, 2023). "Concomitant with increased ventricular pressure, Piezo1, as a newly recognized mechano-sensitive cation channel, was the most up-regulated mechanosensor in the myocardium of patients with advanced heart failure." (PMID 37303604, 2023).
alcoholic liver diseases (1 paper, 2024). A disorder caused by damage to the liver parenchyma due to alcohol consumption. "UK Biobank data, which are primarily from white British people, indicated associations of PIEZO1 variants with death attributed to fatty liver, alcoholic liver disease, and liver biliary pancreas problems." (PMID 39331703, 2024).
Alpha-thalassemia (1 paper, 2023). Alpha-thalassemia is an inherited hemoglobinopathy characterized by impaired synthesis of alpha-globin chains leading to a variable clinical picture depending on the number of affected alleles. "Subsequent NGS analysis uncovered a whole-gene deletion of HBA1 and HBA2, alongside an LP/P variant in PIEZO1, leading to a conclusive diagnosis of alpha thalassemia minor combined with dehydrated hereditary stomatocytosis." (PMID 37697358, 2023).
aortic valve stenosis (1 paper, 2024). Aortic valve stenosis (AVS) is a condition characterized by narrowing of the heart's aortic valve opening. "In aortic valve stenosis, Piezo1 was identified as the main mechanoreceptor responsible for driving monocyte and plasma inflammatory phenotypes." (PMID 38267432, 2024).
arteriosclerosis (1 paper, 2025). A vascular disorder characterized by thickening and hardening of the walls of the arteries. "In the process of arteriosclerosis, Piezo1 dysfunction is closely associated with pathological changes in VSMCs." (PMID 41195420, 2025). "Research has found that Piezo1 expression is significantly upregulated in arteriosclerosis patients, which is closely related to smooth muscle cell proliferation and migration, thus promoting the progression of arteriosclerosis." (PMID 41195420, 2025). "By modulating Piezo1 function, new approaches for treating arteriosclerosis may be developed." (PMID 41195420, 2025).
Ascites (1 paper, 2025). Accumulation of fluid in the peritoneal cavity (between the layers of the peritoneum that lines the abdomen). "Thus, the critical contribution of Piezo1 to the formation of ascites in liver cirrhosis is revealed." (PMID 41034523, 2025). "In conclusion, Piezo1 in endothelium contributes to the formation of portal hypertensive ascites via the NF-ĸB−AQP1 pathway in liver cirrhosis, which indicates that blockage of the Piezo1−NFĸB−AQP1 pathway may be a useful strategy for the management of ascites in liver cirrhosis." (PMID 41034523, 2025).
Bardet-Biedl syndrome 12 (1 paper, 2021). Any Bardet-Biedl syndrome in which the cause of the disease is a mutation in the BBS12 gene. "These variations were present in genes BBS12, STIL, COG6 and PIEZO1.A mutation in BBS12 causes Bardet-Biedl syndrome 12 (OMIM #615989)." (PMID 33772059, 2021).
bladder disorder (1 paper, 2024). "However, no human bladder disorder has been associated with dysregulation of PIEZO1." (PMID 38184690, 2024).
bladder tumor (1 paper, 2025). "The tissue chips from 181 BLCA patients with T1‐stage who underwent transurethral resection of bladder tumor (TURBt) were utilized to analyze the expression profile and clinical significance of the Piezo1/ITGB1 axis." (PMID 40667648, 2025).
Candida infection (1 paper, 2023). "Previous work identified several exogenous stressors (antibiotics, anticancer drugs, ultraviolet radiation, and Candida infection) as activators of this SFK-p38-EGFR axis; however, our work proposes endogenous mechanical forces activating this same axis via Piezo1." (PMID 37756411, 2023).
cerebral cavernous malformation (1 paper, 2025). A disorder characterized by malformations in the structure of the capillaries in the brain. "Finally, a novel PIEZO1 missense mutation was recently shown to segregate within a family, together with the cerebral cavernous malformation (CCM) phenotype." (PMID 40282211, 2025).
Chronic colitis (1 paper, 2023). A chronic inflammatory disease of the large intestine (colon, cecum and rectum). "In a mouse model of chronic colitis, Piezo1 in CD4+ T cells was critical for development of intestinal inflammation, raising the possibility that Piezo1 activation could promote intestinal inflammation." (PMID 37781915, 2023).
chronic pancreatitis (1 paper, 2022). A chronic inflammatory process causing damage and fibrosis of the pancreatic parenchyma. "Thus, high pressure within the pancreas stimulates Piezo1 channel opening, and subsequent activation of TRPV4 leads to stellate cell activation and pressure-induced chronic pancreatitis and fibrosis." (PMID 35451372, 2022). "It will be interesting to evaluate Piezo1 and TRPV4 in stellate cells of patients with chronic obstructive pancreatitis and to determine if administration of a Piezo1 or TRPV4 blocker can block or reverse obstructive chronic pancreatitis and fibrosis in humans." (PMID 35451372, 2022). "If pathological effects of Piezo1 (high-pressure–induced stellate cell activation and fibrosis) require TRPV4 channels, we would expect that mice lacking TRPV4 would be protected against pressure-induced chronic pancreatitis and fibrosis." (PMID 35451372, 2022).
colorectal adenocarcinoma (1 paper, 2025). The most common type of colorectal carcinoma. "In contrast, studies on colorectal adenocarcinoma have demonstrated increased PIEZO1 expression in poorly differentiated tumors compared to well-differentiated ones and to adjacent non-malignant tissues." (PMID 40724850, 2025).
colorectal polyposis (1 paper, 2025). "While predisposing variants in genes such as NTHL1, MSH3, POLE, POLD1, DSC2, and PIEZO1 have been associated with colorectal polyposis, they do not fully mimic the classical FAP phenotype." (PMID 41204315, 2025).
craniosynostosis (1 paper, 2023). Craniosynostosis is defined as the premature fusion of one or more cranial sutures leading to secondary distortion of skull shape resulting in skull deformities with a variable presentation. "Treating craniosynostosis mice with Yoda1, a small molecule agonist for Piezo1, reduces intracranial pressure and improves CSF flow, in addition to restoring meningeal lymphangiogenesis, drainage to the deep cervical lymph nodes, and brain-CSF perfusion." (PMID 37917195, 2023).
deafness (1 paper, 2023). An inherited or acquired condition characterized by the complete loss of the ability to hear from one or both ears. "There were no instances of multiple variants being identified in the same gene, and only two were in known deafness genes, S1PR2 and PIEZO1." (PMID 38011198, 2023).
Duchenne muscular dystrophy (1 paper, 2024). Duchenne muscular dystrophy (DMD) is a neuromuscular disease characterized by rapidly progressive muscle weakness and wasting due to degeneration of skeletal, smooth and cardiac muscle. "GsMTx4 is an inhibitor of Piezo1 and Piezo2 and has been used to treat Duchenne muscular dystrophy." (PMID 39104594, 2024).
endometrial cancer (1 paper, 2021). Primary or metastatic malignant neoplasm involving the endometrium (mucous membrane that lines the endometrial cavity). "• Establishment of endometrial cancer (-predisposed) organoid models.• Significant differences compared to healthy endometrium in PIEZO1 and transient receptor potential channels." (PMID 33959613, 2021).
endometriosis (1 paper, 2026). The growth of functional endometrial tissue in anatomic sites outside the uterine body. "Thus, we investigated the occurrence and localization of Piezo1 and Piezo2 in healthy human endometrium and in endometriosis using immunohistochemistry." (PMID 41594706, 2026). "The ion channels Piezo1 and Piezo2 primarily work as mechanosensors and mechanotransducers but also have functions that could participate in the clinical hallmarks of endometriosis." (PMID 41594706, 2026).
erectile dysfunction (1 paper, 2023). Persistent or recurrent inability to achieve or to maintain an erection during sexual activity. "Further studies are necessary to determine its role in penile erection and if erectile dysfunction is associated with Piezo1 deficiency." (PMID 36846322, 2023).
G6PD deficiency (1 paper, 2021). An X-linked genetic condition caused by alterations in the gene G6PD that result in moderately to severely decreased activity levels of the enzyme glucose-6-phosphate dehydrogenase. "In this series we found the association of G6PD deficiency and PIEZO1 stomatocytosis in two female patients (mother and daughter) with suspected hereditary stomatocytosis." (PMID 34093240, 2021).
hemochromatosis (1 paper, 2024). A disorder of iron metabolism characterized by a triad of HEMOSIDEROSIS; LIVER CIRRHOSIS; and DIABETES MELLITUS. "The GWAS of UK Biobank uncovered that 30 genetic loci were associated with VVs; the strongest associations found three SNPs in the CASZ1, PIEZO1, and 50 kB upstream to the HFE (hemochromatosis) genes." (PMID 39858587, 2024).
hemorrhage (1 paper, 2025). Loss of blood from the vascular compartment to the exterior or into nonvascular body space as a result of rupture or severance of the blood vessels. "In models of cerebral hemorrhage, suppressing PIEZO1 alleviates endoplasmic reticulum stress and apoptosis in oligodendrocytes, thereby protecting myelin and improving neurological function after hemorrhage." (PMID 40703567, 2025).
Hirschsprung disease (1 paper, 2024). Hirschsprung disease (HSCR) is a congenital intestinal motility disorder that is characterized by signs of intestinal obstruction due to the presence of an aganglionic segment of variable extent in the terminal part of the colon. "Further investigations into the underlying molecular mechanisms and signaling pathways associated with Piezo1-mediated effects in the ENS may reveal new therapies for congenital and acquired diseases of the ENS, such as Hirschsprung disease." (PMID 39759870, 2024). "Future investigation of the role of Piezo1 in congenital diseases of ENS development, such as Hirschsprung disease, may reveal new pathways of disease pathogenesis and open potential avenues for therapy." (PMID 39759870, 2024).
Hyperinsulinemia (1 paper, 2025). An increased concentration of insulin in the blood. "The hyperinsulinemia associated with T2DM may exacerbate normal Piezo1-dependent Ca2+ uptake into RBCs, contributing to RBC dysfunction and circulatory complications in T2DM." (PMID 40483587, 2025).
Hyperkalemia (1 paper, 2025). An abnormally increased potassium concentration in the blood. "Spironolactone was not initiated due to preexisting hyperkalemia, which is also a manifestation of PIEZO1 GOF mutations." (PMID 41237237, 2025).